CDH1 (cadherin 1)
Diseases named in the same sentence as CDH1 in open-access papers (continued):
Sharing a sentence is not in itself a finding about the gene and the disease.
cancer (continued). "As with CDH1, for every site the SEER proportion of patients diagnosed with regional or distant disease exceeded our observed prevalence of primary carcinomas with at least one CTNNB1 mutation." (PMID 29156750, 2017). "As with carcinoma, the epithelial marker CDH1 was downregulated in UM and down more in MetUM compared to the untransformed NUM, while the mesenchymal marker CDH2 was upregulated in UM and up more in MetUM." (PMID 28246385, 2017). "It has been proven that the loss of the epithelial marker, E-cadherin (E-cad/CDH1), is a causal factor in cancer progression." (PMID 27588490, 2016). "Mutations in CDH1 (OR=0.12, CI=0.034–0.38) and ERBB2 (OR=0.16, CI=0.042–0.59) were uncommon in ER− cancers, but were associated with lower grade." (PMID 27161491, 2016). "We next sought to investigate how the Cdh1/WWP2 signaling axis impinges on the tumorigenicity of cancer cells." (PMID 27462441, 2016). "On the contrary, the down-regulation of EMT-inducing gene expression restores CDH1 expression and leads to the attenuation of cancer malignancy through a mechanism referred to as mesenchymal to epithelial transition (MET), the reverse program of EMT." (PMID 27258152, 2016). "In good agreement with this model, Cdh1 inactivation leads to the development of several cancers in mice, and low Cdh1 expression was observed in multiple cancer cell lines." (PMID 26650195, 2016). "Additional 69 candidate genes of interest related to epithelial-mesenchymal transition and the study of metastatic behavior in cancer cells (e.g., CDH1) were also added to the assay." (PMID 27623752, 2016). "As a result, Cdh1 modulates the PI3K/Akt signaling pathway by influencing WWP2-mediated degradation of PTEN in cancer cells to govern tumorigenesis." (PMID 27462441, 2016). "In PDCD4-knockdown cancer cells, epithelial cadherin 1 (E-cadherin) promoter activity was inhibited." (PMID 27852288, 2016). "Cdh1-kd led to increased proportion of S phase cells confirming previous results in other cancer cell lines compared to a decrease when Skp2 was depleted." (PMID 27374082, 2016). "Concomitant with downregulation of Cdh1 expression, several APC/C–Cdh1 targets, such as Aurora A, Aurora B, Cdc6, Cdc20, Cyclin B, Rad17 and Tpx2 are often upregulated in human cancer tissue samples." (PMID 27418942, 2016). "E-cadherin (CDH1) is a glycoprotein that mediates adhesion between epithelial cells and also suppresses cancer invasion." (PMID 27811364, 2016). "Therefore, the loss of CDH1 may also contribute to the development of many other types of cancers." (PMID 27600761, 2016). "The down-regulation of E-cadherin gene (CDH1) expression has been regarded as an important event in cancer invasion and metastasis." (PMID 27067410, 2016). "CDH1 is localized to the surface of growing cancer cells and plays a major role in the formation of cell–cell contacts and is responsible for the maintenance of the cell polarity." (PMID 27303212, 2016). "The role of adhesion molecules such as integrins and E-cadherin (CDH1), in intra-cellular cancer cell signal transduction have been elucidated previously, including HCC." (PMID 27303212, 2016). "CDH1 and CDH2 are expressed in most normal tissues and reduced or loss of expression in cancer cells is well documented." (PMID 26011628, 2015). "CDH-1 gene expression in malignant neoplasms and in normal mammary tissue was similar between diestrous and spayed (p ≥ 0.23), and between diestrous and anestrous dogs (p ≥ 0.33)." (PMID 26370564, 2015).
cancer (continued). "Among diestrous bitches, CDH-1 gene expression was highest in benign neoplasms compared to normal mammary tissue and malignant neoplasms (p = 0.001 and p = 0.008, respectively)." (PMID 26370564, 2015). "We genotyped 12 haplotype-tagging single nucleotide polymorphisms (htSNPs) in CDH1 and CTNNB1 among 1,160 BC cases and 1,336 age-matched cancer-free controls using the TaqMan® Genotyping Assay." (PMID 26285011, 2015). "TGF-β-induced EMT can be suppressed by miR-147, independently of other miRs such as the miR-200 family members, through the translational inhibition of ZEB1 and the upregulation of CDH1 in cancer cells." (PMID 24454732, 2014). "CDH1 and SFN are important tumor suppressor genes whose loss of function has been implicated in many types of cancers." (PMID 25286960, 2014). "If the products generated from alternative pre-mRNA splicing of CDH1 are identified, it will be possible to treat cancer patients more selectively." (PMID 25184143, 2014). "Specifically, we examined sensitivity of cancer cells in the presence of mutations and/or over-expression of BRAF, CDH1, ERBB2, CCND1 and MET." (PMID 24884660, 2014). "The frequency of CDH1 methylation in the subjects with GC was significantly lower in cancer lesion than in non cancerous mucosa, whereas that of DAPK methylation was not different." (PMID 23280118, 2013). "The frequency of CDH1 methylation in the subjects with GC was significantly lower in cancer lesion than in non cancerous mucosa (78/115 vs. 96/115, p = 0.009)." (PMID 23280118, 2013). "Our results demonstrated that 5 of the 6 up-regulated mRNAs in “HTLV-1 infection pathway” increased (ICAM1, WNT2B, MYC, HLA-F and TGF-β1) and 3 of the 5 down-regulated mRNAs in “Pathways in cancers” decreased (CDH1, PTENP1, HSP90AA1)." (PMID 24367666, 2013). "The ZEB1 transcription factor is best known as an inducer of epithelial-mesenchymal transitions (EMT) in cancer metastasis, acting through transcriptional repression of CDH1 (encoding E-cadherin) and the EMT-suppressing microRNA-200s (miR-200s)." (PMID 23667256, 2013). "In the samples from cancer-adjacent normal tissues, 4 (4.3%) of 92 specimens were partially methylated (U/M) in CDH1 gene promoter." (PMID 22514028, 2012). "Methylation in only two genes (CDH1, p16) was examined in more than one study, and both were significantly different in frequency in the samples from GC and non-cancer subjects in meta-analysis." (PMID 22558417, 2012). "Epigenetic inactivation of CDH1 is thought to contribute to progression in cancer by increasing proliferation, invasion, and/or metastasis." (PMID 21639921, 2011). "Allelic expression imbalance has also been studied in the cancer associated genes BRCA1/2 and CDH1 and used to identify polymorphisms, mutations and other defects that alter allelic expression and influence disease state." (PMID 21345208, 2011). "The hypermethylation of the promoter of the gene CDH1 was detected in 11 out of 17 cases that reported positive familial history of cancer." (PMID 16512896, 2006). "Cancer-specific outcomes in AYA with germline CDH1 P/LP variants who pursue active surveillance are no different than those who had PTG." (PMID 39760880, 2025). "Emerging evidence suggests that APC/C and its co-activators (CDC20/CDH1) may influence cancer progression beyond cell cycle regulation, potentially through modulation of EMT and MMP pathways." (PMID 40136519, 2025). "Given that M2 macrophages are known to induce epithelial‐mesenchymal transformation (EMT) in cancer cells, we explored the correlation between VSIG4 and several biomarkers associated with EMT processes (MMP9, SNAI1, SNAI2, VIM, TWIST1, TWIST2, CDH1, CDH2) in CRC through the TIMER2.0 website." (PMID 40405491, 2025).
cancer (continued). "The penetrance of CDH1 mutations in families with HDGC is significant, with studies suggesting that 70%-80% of carriers may develop associated cancers." (PMID 40585607, 2025). "mG1 cancer cells also seem more prone to EMT, possibly because of mutations in CDH1." (PMID 40740860, 2025). "The data presented here reinforce previous work that SRC are an expected finding in germline CDH1 P/LP variant carriers and do not herald clinically actionable cancer." (PMID 39760880, 2025). "In conclusion, our results show that, in addition to CDH1 and CTNNA1 testing in families fulfilling the HDGC criteria, multi-organ cancer predisposition genes should be included in gene panels used for investigating germline variants in patients with diffuse and non-diffuse GC." (PMID 40446793, 2025). "CDH1 (E-cadherin or CD324), a classical cadherin expressed by epithelial cells that prevents cancer cell invasion by maintaining cell-cell adhesions (Pećina-Šlaus, 2003), was identified only in the cancer cells, in very low abundance in MDA-MB-231 and somewhat higher abundance in SK-OV-3 cells." (PMID 41279931, 2025). "In addition, silencing DNMT1, which leads to the upregulation of CDH1, also known as the DNMT1/CDH1 loop, in the presence of excessive ectopic expression of miR‐152 effectively inhibits the migratory capability of cancer cells." (PMID 40387409, 2025). "Owing to the important role of E-cadherin at cell‒cell contacts, controlling the expression of its encoding gene, CDH1, has also been reported to have important implications for both development and cancer." (PMID 39833727, 2025). "The roles of CDH1 in metabolic reprogramming may also explain why the Warburg effect and other metabolic changes are observed not only in cancer cells but also in proliferating non‐cancerous cells." (PMID 41020695, 2025). "Therefore, we measured the effect of sgRNAs for ZEB1 on CDS1 expression by qPCR and computationally scored the correlation between the expression of ZEB1 and CDS1 or CDH1 across cancer types in the DepMap." (PMID 40615674, 2025). "Additionally, genetic mutations in the CDH1 gene are linked to HDGC, underscoring its importance in cancer predisposition." (PMID 40585607, 2025). "The results of germline genetic testing in a single commercial laboratory in over 200,000 probands with a variety of cancers reported a significant enrichment of germline CDH1 PV in patients with colorectal adenocarcinoma (CRC) and signet ring cell cancer when compared to a cancer-free population." (PMID 40323501, 2025). "Furthermore, when expanding this comparison with healthy tissue to 16 cancer types covering CDS1 and CDH1, we observed that both genes are expressed at low levels in mesenchymal-like cancer cell lines." (PMID 40615674, 2025). "Finally, we analyzed the association of CDH1 and PIK3CA with specific biological processes at pan-cancer level." (PMID 41404730, 2025). "Thus, APC/CCDH1 is likely the physiological E3 ubiquitin ligase for PIN1, and its activity is primarily inhibited by phosphorylation of CDH1 in cancer cells." (PMID 38622115, 2024). "In breast cancer, there exists a concordance between heightened TGF‐β–Smad2 pathway activation and the DNA methylation‐mediated silencing of CDH1, implicating a complex interplay between signaling pathways and epigenetic modifications in the cancer metastasis narrative." (PMID 38374872, 2024). "Over the last decades, the role of CDH1 in cancer aetiology has been extensively investigated." (PMID 38414029, 2024). "In a previous study, downregulation of the Cdh1 gene will affect the proliferation of cancer cells." (PMID 38038259, 2024).
cancer (continued). "Therefore, soluble Cdh1 NTF serves as an important biomarker for many types of cancer and predicts a higher aggressiveness of tumors." (PMID 39000189, 2024). "Moreover, a heatmap depicting ZEB1, ZEB2, CREB3L1, and CDH1 across the nine ROIs revealed clear segregation between Vim+ and Vim− carcinoma cells." (PMID 39256881, 2024). "Further analysis revealed that our population is enriched for pathogenic variants in ATM, BRCA1, and CDH1 genes and that prevalence of pathogenic variants in the CHEK2 gene is lower in the Slovenian population, when compared to GnomAD non-cancer control population." (PMID 37002323, 2023). "Moreover, the downregulation of CDH1 was detected at 24 h of incubation of cancer cells with mEV from CRC patients vs. mEV from HS and HT29 cells cultured alone; mEVs from HS did not significantly affect EMT gene markers." (PMID 36672299, 2023). "Further tests of these FAK inhibitors (3 or 5 μM) combined with crizotinib or entrectinib (30 μM to 4.572 nM) resulted in the dose-dependent inhibition of cancer cell growth in non-resistant CDH1-deficient cell lines that was stronger than either monotherapy." (PMID 37324948, 2023). "Consistently, PSAT1 knockout could change the morphology of cancer cell lines (PLC/PRF/5) containing p5372P variants and increase the mRNA level of CDH1." (PMID 36788227, 2023). "Unfavorable CDH1 downregulation was detected in both cell lines under normoglycemic conditions, once again indicating a positive impact of increased glucose levels on metformin-induced expression changes of cancer-related genes." (PMID 37313172, 2023). "Cancer cell 3 represented the early-stage cancer-initiating cells with the expression of acinar cell genes such as Clps, Try4, and Try5, as well as epithelial marker genes such as Epcam and Cdh1." (PMID 37998349, 2023). "Previous studies showed the role of Cdh1 in different types of cancers." (PMID 38188879, 2023). "In HDGC patients with CDH1 heterozygous germline mutations, E-cadherin is not expressed in cancer cells, and the evidence of p120 protein cytoplasm positive also supports the theory of biallelic inactivation." (PMID 37393258, 2023). "In the network, eight genes related to the apoptotic process and cell migration, including Mmp9, Cxcl12, Cdh1, Fap, Itga6, Mdk, Aif1, and Mif, were downregulated with co-treatment, which may play vital roles in inhibition of cancer progression and cell death." (PMID 36765032, 2023). "We performed cancer patient survival analysis to assess whether the CDH1 mRNA expression is correlated to cancer patient’s survival." (PMID 37189027, 2023). "Indeed, Jakubowska and colleagues have sequenced the entire coding region of CDH1 gene in 86 Polish cancer patients from families fulfilling the criteria of HDGC and have found no deleterious mutations in the CDH1 gene." (PMID 36011265, 2022). "Additionally, in MCF-7 cells, SETD7 knockdown induced the purported cancer stem-like cell phenotype (CD44+/CD24−/low) and dedifferentiation of mammospheres associated with loss of cadherin-1." (PMID 35326563, 2022). "However, there is some evidence that high CDH1 expression is related to a worse prognosis; thus, the contribution of CDH1 to cancer progression needs further investigation." (PMID 36142368, 2022). "This combination was neither significantly synergistic nor antagonistic in CDH1−/− cells, suggesting that this drug combination will not be useful for targeting E-cadherin-deficient cancers." (PMID 35406381, 2022). "Hence, we analyzed TCGA expression data from 32 cancer types (∼9,000 patient samples) to identify LncRNAs associated with EMT markers, VIM, FN1, SNAI1, SNAI2, and CDH1 (and material and method)." (PMID 36120580, 2022). "All these findings implied that CDH1 would be a potential therapeutic target for cancers." (PMID 36131343, 2022). "CDH1 is commonly reported as a tumor suppressor gene in cancer literature." (PMID 35784532, 2022).
cancer (continued). "The lower urinary levels of cadherin-1 or epithelial (E)-cadherin (PCa2 vs. Cont2) may be related to the down-regulation of this protein in cancer cells." (PMID 35886909, 2022). "The availability of these approved, well-tolerated, oral drugs as well as simple methods for assessing CDH1 expression could enable rapid translation of these findings to improve cancer patient outcomes." (PMID 36280687, 2022). "Patients who inherit a CDH1 mutation should undergo total gastrectomy, they should not wait until there is biopsy proof of cancer or symptoms develop." (PMID 35158993, 2022). "But it may be a repressor for CDH1 transcription in cancer cells because of blocks of the nucleus‐cytoplasm shift by the decreased level of Kaiso phosphorylation." (PMID 35851744, 2022). "Although CDH1 loss is a necessary initial event in gastric carcinogenesis, re-expression of CDH1 during cancer progression could represent a confounding factor in identifying useful targets for combined drug treatments." (PMID 36556227, 2022). "Our results suggest that CDH1 may play an important role in the pathways in cancer signaling pathway that regulate ACP development." (PMID 36387067, 2022). "The prevalence of CDH1 germline variants in patients with various cancer types is still not well-described." (PMID 34949788, 2022). "In contrast, the decreased level or deprivation of pT606 phosphorylation of Kaiso could block the cytoplasmic transportation of Kaiso, repress CDH1 transcription and promote the growth of cancer cells." (PMID 35851744, 2022). "Moreover, repression of E-cadherin (CDH1) by SALL4 modulates cell dispersion in basal-like cancer types." (PMID 36010677, 2022). "We found that CDH1 may play an important role in the pathways in cancer signaling pathway that regulates ACP development." (PMID 36387067, 2022). "Depletion of the T606 phosphorylation of Kaiso could augment repression of CDH1 expression and promote cancer cell growth in vivo." (PMID 35851744, 2022). "In order to evaluate the effect of RNase A on metastasis development, we investigated the expression of markers associated with epithelial–mesenchymal transition (EMT): Cdh1 (E-cadherin), Tjp1, Fn and Vim (vimentin), which play important roles in cancer invasion and metastasis." (PMID 35745743, 2022). "This could partly explain why cadherin switching from CDH1 to CDH2 only occurs in 50% of cancer cells that the structural changes from the compact chromatin to the more open euchromatin might require more complex coordination." (PMID 35637517, 2022). "Altered expression of the CDH1 gene is known as a factor of epithelial to mesenchymal transition (EMT), where reduction of CDH1 is associated with increased motility and invasiveness of cancer cells and, hence, a worse prognosis." (PMID 35267318, 2022). "CDH1 was, however, consistently overexpressed in most of the cancer types." (PMID 36120580, 2022). "The first report to state that the CDH1 gene might be affected by aberrant DNA methylation in human carcinoma cells was published in 1995." (PMID 36139537, 2022). "The loss of E-cadherin (CDH1) expression is widely accepted as one of the most important hallmarks of EMT, and it has also been suggested that loss of E-cadherin signifies increased survival for cancer cells." (PMID 33671920, 2021). "Interestingly, among the possible methylation biomarker candidates in both HPV-associated cancers, CC and HNSCC, three genes were considered by different groups: CDH1, CCNA1, and RASSF1." (PMID 34835040, 2021). "As most of our patients have a single CDH1 mutation [NM_004360.4(CDH1):c.2398delC (p.Arg800Alafs)], it is possible that our findings of secondary cancers will not translate across other CDH1 germline mutations." (PMID 34073553, 2021). "CDH1 is a cancer-predisposing gene that is mutated in families meeting the criteria for clinically defined HDGC, with ∼40.0% of HDGC families harboring germline mutations in CDH1." (PMID 34567566, 2021).